ANXA1 (annexin A1)
Diseases named in the same sentence as ANXA1 in open-access papers (continued):
Sharing a sentence is not in itself a finding about the gene and the disease.
Sepsis (continued). "PCR confirmed the significant upregulation of the genes including ANXA1, SIPR1, EDN1, and RSAD2 in the neutrophils samples from patients with sepsis-induced immunosuppression (at 3–4 days and/or 6–8 days post sepsis shock) compared with controls (P < .05)." (PMID 33761636, 2021). "In our previous studies, the expressions of ANXA1 and GATA-3 were both decreased in the burnt mouse with sepsis." (PMID 27833268, 2016). "It is reported that membrane adhesive protein Annexin-A1 (ANXA1) and transcription factor GATA-3, which were both decreased in sepsis patients, play important roles in the Th1/Th2 shift." (PMID 27833268, 2016). "In conclusion, the present study demonstrated that the expression of five proteins (ApoE, Anxa1, NGAL, protein S100a8 and S100a9) was significantly elevated in the progression of sepsis." (PMID 25242054, 2014). "The expression of ApoE, Anxa1, NGAL, S100a8 and S100a9 were all elevated in the progression of sepsis." (PMID 25242054, 2014). "Sepsis was induced in mice using the CLP model, and the expression of ANXA1 was assessed." (PMID 39727329, 2024). "Similarly, lipid-regulating enzymes ANXA1, S100A8, and FABP5 are co-regulated in a network with ApoE and APP in response to sepsis." (PMID 38653992, 2024). "When patients with sepsis classified based on four pro-inflammation and two anti-inflammation cytokines, it was shown that combination of MT-ND6 and ANXA1 obviously improved the predictive values in the septic patients with mixed hyperinflammation or immunosuppression phenotypes." (PMID 39611143, 2024). "This suggests that the knockout of Anxa1 did not induce any alterations in the distribution of inflammatory cells around Vas-1 cells during the simulated sepsis condition." (PMID 38961424, 2024). "Fortunately, we did not give up to explore the potential roles of ANXA1 and captured its decreasing tendency in the septic shock patients when compared with mild sepsis patients (P < 0.05)." (PMID 39611143, 2024). "We employed both wild type and Anxa1−/− C57BL/6 mice as experimental models to investigate the intricate cellular composition and transcriptional pathways in the central nervous system (CNS) during sepsis or SAE." (PMID 38961424, 2024). "Annexin A1 (ANXA1) mimetics, a protein involved in the resolution of inflammation, have been effective in animal models of inflammation including arthritis, colitis, and sepsis." (PMID 38317257, 2024). "Therefore, using an LPS sepsis model with 4-OI or DMF pretreatment, we found that LPS alone significantly increased annexin A1 in the serum and this was further boosted by 4-OI pretreatment, with a similar trend seen with DMF (p = 0.07)." (PMID 37578391, 2023). "Notably, the key genes upregulated during sepsis are responsible for regulating cell cycle progression and differentiation (i.e., S100A8 and S100A9) and immune responses (i.e., ANXA1, APOBEC3A, LILRA5, CR1, and CD55)." (PMID 37298316, 2023). "Focus was given to the pro-resolving protein AnxA1 and its cognate receptor FPR2/ALX, a pathway that has been shown to exert a degree of protection in experimental tuberculosis, sepsis, pneumococcal pneumonia, and influenza." (PMID 35293862, 2022). "Furthermore, decreased circulating levels of AnxA1 are present in thrombo-inflammatory conditions including ischaemic stroke, SCD, sepsis, Crohn’s disease, and obesity." (PMID 33202930, 2020). "Thus this study, together with our previous observations of ANXA1, suggests that the ANXA1/FPRL-1 axis and GATA-3 are potential therapeutic targets of the Th1/Th2-mediated immunological suppression in sepsis." (PMID 27833268, 2016). "It is proposed that the interactions between ANXA1 and GATA-3 may provide clues to understand the immunosuppression and have potential as new therapeutic targets in immunotherapy after sepsis." (PMID 27833268, 2016).
Sepsis (continued). "Our previous animal model observed that ANXA1 and GATA-3 both present the same downtrend in mouse with severe sepsis; this phenomenon may be related with a large number of T cells apoptosis." (PMID 27833268, 2016). "Exploring the interactions between ANXA1 and GATA-3 may provide clues to understand the immunosuppression and improve the treatment effects of sepsis patients." (PMID 27833268, 2016). "ANXA1 and FPR1 play a crucial role in the occurrence of adrenal insufficiency by regulating cholesterol ester storage and may represent a novel therapeutic target for maintaining adrenal cortex hormone synthesis in sepsis patients." (PMID 40426888, 2025). "However, there is no direct evidence of MT-ND6 or ANXA1 in the circulation of patients with sepsis and their potential role in clinical significance, including diagnosis and mortality prediction during sepsis." (PMID 39611143, 2024). "Additionally, the concentration of MT-ND6 was increased with the severity of sepsis patients and SOFA score values, but no statistical difference was observed in the levels of ANXA1." (PMID 39611143, 2024).
colitis (25 papers, 2012 to 2025). Inflammation of the colon. "The use of Ac2‐26, a peptide that mimics annexin A1, in experimental colitis models has been found to cause changes in the makeup of the intestinal microbiota." (PMID 40589771, 2025). "Most directly, a preclinical study demonstrated that manipulating of AnxA1 levels alters gut microbial composition and modifies susceptibility to DSS-induced colitis, supporting a causal role for AnxA1 in microbiota-host crosstalk." (PMID 41550928, 2025). "Protective role: AnxA1 deficiency worsens colitis; Ac2–26 or AnxA1 nanoparticles improve histology, ↑IL-10 and efferocytosis, ↓inflammation." (PMID 41550928, 2025). "Pre-clinical studies have demonstrated that AnxA1 KO mice presented increased susceptibility to DSS-induced colitis, showing worse histologic scores and increased mucosal injury than the respective wild type controls." (PMID 33807591, 2021). "It has been shown that ANXA1-deficient animals exhibit increased susceptibility to dextran sulphate sodium (DSS)-induced colitis with greater clinical morbidity and histopathologic mucosal injury." (PMID 33672304, 2021). "ANXA1 knockout mice (AnxA-/-) exhibited higher susceptibility to DSS-induced colitis." (PMID 39428941, 2025). "Single-cell profiling in colitis further confirms enrichment of ANXA1 in epithelial and CD4+ T-cell subsets involved in mucosal healing." (PMID 41550928, 2025). "Further, Annexin A1 secretion, by infiltrating neutrophils and macrophages, is a feature of a chemically-induced rat model of colitis." (PMID 35563776, 2022). "The administration of MC-12, an ANXA1 based peptide, was shown to be effective in the amelioration of colitis symptoms in DSS and TNBS IBD models." (PMID 33807591, 2021). "In an experimental in vivo model, the application of exogenous ANXA1 mimetic peptide (Ac2-26) encapsulated in polymeric nanoparticles enhanced healing of murine colonic wounds and improved recovery from induced colitis." (PMID 33672304, 2021). "As expected, colitis induced significant weight loss and increased the DAI in both WT and AnxA1−/− strains." (PMID 34603288, 2021). "To explore the mechanisms involved in the efficacy of IFX, we performed DSS-induced colitis in WT and AnxA1−/− C57BL6 mice and followed up to the late phase of the disease." (PMID 34603288, 2021). "Our choice was also supported by the increased AnxA1 secretion upon IFX in experimental colitis and its correlation with tissue recovery." (PMID 34603288, 2021). "Intracellular and FPR-binding AnxA1 mediate inflammation resolution and tissue repair on experimental colitis." (PMID 34603288, 2021). "Using the dextran sulfate sodium colitis model in mice, we suggest that infliximab induces annexin A1 expression and secretion in activated intestinal leukocytes." (PMID 34603288, 2021). "Previously, we reported the relevance of AnxA1 in the efficacy of IFX during acute colitis in female Balb/c mice." (PMID 34603288, 2021). "Annexin A1 (ANXA1) facilitates the repair of intestinal mucosal wounds in a murine model of colitis, and their release is elevated during wound closure." (PMID 32410847, 2020). "Data obtained in the present work evidence pioglitazone attenuates inflammation in vivo in a murine colitis model, and prevention of AnxA1 cleaving seems to be involved with such effect." (PMID 33519451, 2020). "Meanwhile, the endogenous molecule annexin A1 (ANXA1) has been reported to promote epithelial restitution in a colitis-induced mucosal damage model." (PMID 32410847, 2020). "Experimental colitis was evoked by 2% dextran sodium sulfate (DSS) in AnxA1 knockout (AnxA1−/−) or wild type (WT) C57BL/6 mice." (PMID 33519451, 2020). "Overall, our main findings evidence pioglitazone relies on AnxA1 expressed by macrophages to exert its anti-inflammatory actions throughout the course of experimental colitis, and that it does so by preventing AnxA1 cleaving." (PMID 33519451, 2020).
colitis (continued). "As it was evidenced AnxA1 is necessary for the anti-inflammatory effects of pioglitazone on DSS-induced colitis, its expression and cleaving status were assessed in WT mice." (PMID 33519451, 2020). "We also assessed IL-10 and Annexin A1 levels, which are known to exert anti-inflammatory roles during colitis, using ELISA and immunohistochemistry, respectively." (PMID 30455703, 2018). "The contribution of AnxA1 to the remission of IBD was validated with a model of dextran sulfate sodium (DSS)-induced colitis in TNFR knockout (KO) mice, mimicking the anti-TNF-α therapy." (PMID 27199985, 2016). "Increased intestinal tissue injury in the murine model of experimental colitis using ANXA1-/- mice provides further support that ANXA1 is important for controlling intestinal inflammation and maintaining functional mucosa." (PMID 24130820, 2013). "Our results confirmed that the lack of endogenous AnxA1 is very detrimental to the progression of experimental colitis: AnxA1−/− mice had much worse clinical and histological outcomes, fewer intestinal regulatory T cell (Treg) counts, and a 25% mortality rate compared to WT mice." (PMID 34603288, 2021). "Local expression of AnxA1 is pivotal to tissue recovery in CD and experimental colitis." (PMID 34603288, 2021). "Colitis upregulated AnxA1 in the damaged epithelium from the DSS and DSS+Boc-2 groups." (PMID 34603288, 2021). "Moreover, AnxA1 peptides encapsulated in nanoparticles accelerated the recovery of experimentally induced colitis and the healing of colonic biopsy-induced wounds." (PMID 27199985, 2016). "Annexin A1 levels increase during DSS colitis, with the molecule acting through the FPRL1; however, we speculated that mucosal levels of annexin A1 might be upregulated by signals through the FPR1 acting as a sensor for invasive bacteria." (PMID 22383080, 2012). "Additionally, the therapeutic administration of nanoparticles containing the AnxA1 mimetic peptide Ac2-26 after DSS withdrawal produced a faster recovery of the colitis symptoms as compared to mice that were inoculated with nanoparticles containing a scrambled peptide." (PMID 33807591, 2021). "AnxA1-based mimetics (e.g., Ac2-26), FPR2/ALX agonists, and targeted nanoparticle formulations have shown anti-inflammatory benefits in experimental colitis." (PMID 41550928, 2025). "This phenomenon was reproduced in the DSS-induced colitis treated with IFX, as colon explant supernatants had increased levels of AnxA1 compared to the control group." (PMID 34603288, 2021). "Thus, our data suggest that pioglitazone might indeed be linked to AnxA1 in order to exert its anti-inflammatory actions during the progression of DSS-induced colitis, but by modulating its functionality rather than its overall expression." (PMID 33519451, 2020). "Furthermore, administration of an exogenous glucocorticoid-regulated protein annexin A1 (ANXA1) mimicking peptide encapsulated within targeted polymeric nanoparticles significantly accelerated healing of mucosal wounds in experimentally DC-derived induced colitis." (PMID 26631254, 2015). "A previous study showed that the endogenous FPR ligand, annexin A1, could regulate the intestinal mucosal injury, inflammation and repair through stimulation of FPRL‐1 in DSS‐induced colitis." (PMID 33300279, 2021). "Pioglitazone treatment did not attenuate clinical parameters of colitis in AnxA1−/− mice, and disease scores remained comparable to that of non-treated animals." (PMID 33519451, 2020). "In line with this, one of the major protein components of resolution cascade, ANXA1, has been extensively studied by its actions on neutrophil infiltration blockade in acute models of inflammation, such as acute murine MSU-induced gout, DSS-induced colitis, zymosan-induced peritonitis, among others." (PMID 33807591, 2021). "In turn, AnxA1 was weakly detected in tissue leukocytes in non-treated colitis." (PMID 34603288, 2021).
colitis (continued). "Data here obtained corroborated other studies which already evidenced the beneficial actions of pioglitazone in murine models of colitis and evidenced the lack of pioglitazone effects on AnxA1−/− mice demonstrating the pivotal role of AnxA1 for pioglitazone anti-inflammatory actions." (PMID 33519451, 2020). "Indeed, DSS-colitis in AnxA1−/− mice is more pronounced and leads to increased mortality and AnxA1 expression in the colon of WT mice increased regardless of treatment with pioglitazone." (PMID 33519451, 2020). "The effect of AnxA1 or its peptides on epithelial cell barrier has not been studied in intestinal I/RI models but they have afforded protection in other gastrointestinal inflammatory murine models including colitis and gastric ulcers." (PMID 29659553, 2018). "In addition, AnxA1 deficient mice failed to regain weight and showed no improvement in disease activity index and mucosal injury upon withdrawal of disease in the DSS-induced colitis model, advocating the crucial and beneficial role of AnxA1." (PMID 29659553, 2018). "Mucosal levels of AnxA1 increased in the absence of TNF-α signaling, allowing early recovery of colitis as compared to wild-type (WT) mice." (PMID 27199985, 2016).
glioblastoma (24 papers, 2012 to 2025). The most malignant astrocytic tumor (WHO grade IV). "In the tumor landscape, one of the first indications that AnxA1 could promote immune escape came from experiments in which AnxA1 was knocked down in a glioblastoma multiforme animal model and caused decreased tumor growth and myeloid infiltration." (PMID 34571894, 2021). "The expression of ANXA1 was found to be higher in primary glioblastomas as compared to glioblastomas that resulted from the progression of a low-grade astrocytoma, also known as secondary glioblastoma." (PMID 38639785, 2024). "The abundance of ANXA1 was significantly higher in the high-grade glioblastoma EVs compared with low-grade glioblastoma EVs." (PMID 37189694, 2023). "Annexin A1 (ANXA1) is a known regulator in brain tumors like glioblastoma and assists in tumor immune escape through enhanced IL8 production and NF-kB (p65) activation." (PMID 37770851, 2023). "Quantitative mass spectrometry-based proteomic analyses revealed significantly higher ANXA1 protein expression in more invasive glioblastoma cells." (PMID 37189694, 2023). "In highly malignant glioblastoma multiforme (GBM) cells it responds to the endogenous chemotactic ligand ANXA1 released by necrotic GBM cells." (PMID 33804219, 2021). "In this work, the authors suggested that AnxA1 acts in highly malignant and actively growing glioblastomas as a chemoattractant for tumor-promoting myeloid cells, especially granulocytes and macrophages." (PMID 34571894, 2021). "Huang’s and Zhou’s groups showed that AnxA1 or other ligands released by glioblastoma multiforme necrotic cells would mediate FPR1 activation." (PMID 34571894, 2021). "The expression of AnxA1 increased with the degree of malignancy, with overexpression in glioblastomas." (PMID 34650406, 2021). "Our results indicate that inhibition of FoxM1 expression significantly suppresses the tumorigenicity of human glioblastoma cells, whereas rescue the Anxa1 expression can recover the ability of tumorigenicity." (PMID 23991102, 2013). "We first determined the Anxa1 mRNA expression in 30 human glioblastoma (grade 4) and the paired adjacent normal brain specimens by RT-qPCR analyses." (PMID 23991102, 2013). "Significantly higher expression of both FoxM1 and Anxa1 were evident in LN-229and U-87MG glioblastoma cells than in Hs683 and SW1088 cells." (PMID 23991102, 2013). "The publically available human glioblastoma microarray data also showed correlation between FoxM1 and Anxa1 expression (n = 98, r = 0.327, P<0.0001)." (PMID 23991102, 2013). "Our results indicate that suppression of FoxM1 expression inhibit Anxa1 expression in glioblastoma cells." (PMID 23991102, 2013). "Another target of miR196a, Annexin A1 (ANXA1), has also been implicated in glioblastoma as a mediator of apoptosis and an inhibitor of cell proliferation." (PMID 22848219, 2012). "Collectively, these studies suggest that ANXA1 might have a significant role in the development of high-grade astrocytomas and glioblastomas." (PMID 38639785, 2024). "The ANXA1 substrate EGFR was also found to have high expression in primary glioblastomas." (PMID 38639785, 2024). "Finally, analyses of gene expression in human cancer specimens indicates that ANXA1 is overexpressed in CNS tumours, particularly in glioblastoma." (PMID 32921792, 2020). "Specific proteins isolated from glioblastoma exosomes are the invasion-related proteins (Annexin A1 (ANXA1), Insulin growth factor-2, Programmed cell death 6-interacting protein, Actin-related protein 3 and Integrin-β1), and the Polymerase 1 and transcript release factor complex (PTFR)." (PMID 31357616, 2019). "In our study on brain tumor samples from patients, ANXA1 expression levels were assessed using molecular biology techniques and oligonucleotide microarrays and showed an increase in expression of this gene in brain tumors with the highest malignancy, namely glioblastoma multiforme." (PMID 35454784, 2022).
glioblastoma (continued). "FPR1, in malignant glioblastoma multiforme (GBM) cells, is activated by the endogenous chemotactic ligand annexin 1 (ANXA1) released by necrotic GBM cells and functionally interacts with the EGFR to promote survival and invasiveness of GBM cells." (PMID 33923400, 2021). "Compared with ANXA1 and ANXA2, which also are overexpressed in glioblastoma, the expression of ANXA10 is lower in glioblastoma." (PMID 38639785, 2024). "Last, FOXM1 stimulates self-renewal, tumorigenicity and invasiveness of glioblastoma stem-like cells by transactivating a number of molecules, including IPO7 (importing-7), CDC20, PDGF-A, ANXA1, MMP-2 and VEGF." (PMID 27259253, 2016). "Recently, Schittenhelm and colleagues revealed that up-regulation of Anxa1 have a role in the development and/or progression of astrocytomas, and the highest expression were found in WHO grade IV glioblastoma." (PMID 23991102, 2013). "Moreover, prevention of nuclear translocation of ANXA1 using the small peptide Tat-NTS inhibited cellular proliferation (G2/M phase arrest), migration, and invasion of glioblastoma cells." (PMID 37373303, 2023). "Moreover, the tumorigenicity of the glioblastoma cells was significantly reduced in AnxA1 knockout mice, while FPR1/AnxA1 double gene knockout mice were more effective in inhibiting tumor growth than AnxA1 knockout mice." (PMID 34650406, 2021). "Notably, IL-6 and the IL-6 signaling cascade support glioblastoma tumorigenesis and stemness, and we identified that genes involved in the IL-6 signaling pathway, such as ANXA1, LGALS3, and EGFR, were enriched in ICI non-responders pre-ICI 28–30." (PMID 40161763, 2025).